DUXB (double homeobox B)
Gene: Protein-coding gene on chromosome 16 (75,693,893 to 75,701,461, reverse strand). Ensembl gene ENSG00000282757.
Subcellular location: Nucleus
Pathways (Reactome):
Developmental Biology: Zygotic genome activation (ZGA)
Gene Ontology:
Molecular function: DNA-binding transcription factor activity, RNA polymerase II-specific; RNA polymerase II transcription regulatory region sequence-specific DNA binding; DNA binding
Biological process: regulation of transcription by RNA polymerase II; regulation of DNA-templated transcription
Cellular component: nucleoplasm; nucleus
Homologues: Orthologues: chimpanzee DUXB (97% identical), macaque DUXB (89% identical). Paralogues in human: DUX4 (23% identical), PAX7 (14% identical), PAX3 (14% identical), ARX (13% identical), OTP (13% identical), PITX2 (13% identical), ALX4 (12% identical), PAX6 (12% identical), RAX (12% identical), VSX2 (12% identical), OTX1 (12% identical), OTX2 (12% identical), and 38 more.
Diseases named in the same sentence as DUXB in open-access papers:
DUXB is named in the same sentence as 1 disease in open-access papers, as found by Europe PMC text mining. Sharing a sentence is not in itself a finding about the gene and the disease. The quoted sentences say what the papers report.
facioscapulohumeral muscular dystrophy (1 paper, 2025). An autosomal dominant disorder affecting the skeletal muscles of the face, scapula, and upper arm. "In humans, these consist of the three paralogues DUXA, DUXB and DUX4, of which only DUX4 has been extensively characterised due to its roles in facioscapulohumeral muscular dystrophy (FSHD) and multiple cancers." (PMID 40940582, 2025).